ENSG00000273049 (novel protein, readthrough between HOXC10 and HOXC5)
Gene: Protein-coding gene on chromosome 12 (53,985,845 to 54,034,888, forward strand). Ensembl gene ENSG00000273049.
Genetic constraint (gnomAD): Loss-of-function variants: 12 observed, 11.49 expected, observed/expected ratio (o/e) 1.04, 90% interval 0.67 to 1.66. Missense variants: 176 observed, 174.55 expected, observed/expected ratio (o/e) 1.01, 90% interval 0.89 to 1.14. Synonymous variants: 55 observed, 65.28 expected, observed/expected ratio (o/e) 0.84, 90% interval 0.68 to 1.05.